RNU6-566P (RNA, U6 small nuclear 566, pseudogene)
Gene: Small nuclear RNA gene on chromosome 2 (44,154,789 to 44,154,895, reverse strand). Ensembl gene ENSG00000252599.
Homologues: Orthologues: chimpanzee U6 (99% identical), macaque U6 (94% identical), rat LOC120094411 (64% identical), guinea pig U6 (62% identical), tropical clawed frog U6 (60% identical), rabbit U6 (59% identical), mouse Gm25886 (56% identical), mouse Gm55756 (55% identical), guinea pig U6 (52% identical), pig U6 (50% identical), zebrafish U6 (39% identical). Paralogues in human: RNU6-797P (76% identical), RNU6-115P (74% identical), RNU6-445P (74% identical), RNU6-1075P (73% identical), RNU6-1159P (73% identical), RNU6-1327P (73% identical), RNU6-1083P (72% identical), RNU6-1209P (72% identical), RNU6-454P (72% identical), RNU6-879P (72% identical), RNU6-1233P (71% identical), RNU6-1243P (71% identical), and 1284 more.